PRSS42P (serine protease 42, pseudogene)
Description:
Plays a role in spermatogenesis. Involved in germ cell survival during meiosis.
Synonyms: TESSP2; formerly PRSS42
Gene: Transcribed unitary pseudogene on chromosome 3 (46,830,404 to 46,834,095, reverse strand). Ensembl gene ENSG00000178055.
Subcellular location: Cytoplasm; Cell membrane